MTOR (mechanistic target of rapamycin kinase)
Diseases named in the same sentence as MTOR in open-access papers (continued):
Sharing a sentence is not in itself a finding about the gene and the disease.
Cachexia (36 papers, 2011 to 2026). Severe weight loss, wasting of muscle, loss of appetite, and general debility related to a chronic disease. "Muscle mTOR activation is reduced after at least a 12% loss of body weight and further decreases during cachexia progression." (PMID 37217930, 2023). "They showed that this co-culture led to muscle atrophy, associated elevations in cachexia markers, activation of the mTOR/AKT pathway in a time dependent manner, and activation of the STAT3 signalling pathway through EV transfer of PA1." (PMID 37798728, 2023). "In our results, the activated mTOR likely led to an enhanced in hepatic activity, which in the case of cachexia is likely associated with higher liver AMPK, possibly favouring increased gluconeogenesis in these animals." (PMID 34940589, 2021). "In summary, the %MPS reduction during the initiation of cachexia is associated with IGF-1/mTOR signaling repression, while muscle AMPK activation and activation of ATP independent protein degradation occur later in the progression of cachexia." (PMID 21949739, 2011). "Taken together, our data suggest that loss of cardiac mass during the progression of cachexia in the ApcMin/+ mouse is associated with a diminished rate of protein synthesis that is characterized by suppressed mTOR activity and increases in AMPK phosphorylation." (PMID 23589074, 2013). "In contrast to IGF-1 expression, AMPK activation was increased throughout later stages of cachexia, which might explain the decrease in mTOR signaling during extreme body weight loss." (PMID 21949739, 2011). "In an effort to extend our understanding of how cachexia might affect translational signaling in the ApcMin/+ mouse, we next examined whether changes in cardiac mass were associated with differences in the phosphorylation of Akt and mTOR." (PMID 23589074, 2013). "In this context, several studies suggest that muscle atrophy during cachexia is mediated by the suppression of the Akt/mTOR/p70S6K axis." (PMID 40448398, 2025). "In cachexia, chronic PPARγ activation and pioglitazone-induced AMPKα activation converge to suppress mTOR signaling, impair protein synthesis, and promote autophagy through altered energy metabolism (↑ glycolysis, ↑ FA oxidation, ↓ ATP)." (PMID 41476922, 2025). "mTOR activation, often suppressed in cachexia, is crucial for anabolic processes and muscle growth, while AMPK activation in response to energy stress promotes catabolic processes, exacerbating tissue breakdown." (PMID 39409971, 2024). "Taken together, our data suggest that inhibition of mTOR during cachexia can negatively affect autophagy; however, its activation can completely restore muscle mass and function offering an interesting new therapeutic target for cancer cachexia." (PMID 34741441, 2022). "The implication of this is unclear, given that the role of mTOR in adipose tissue in cachexia has thus far been little explored." (PMID 33923976, 2021). "It ameliorates muscle atrophy in cachexia or denervation via activating mTOR signaling pathway or reducing expression of atrogenes, such as MuRF1 and Atrogin-1." (PMID 33935745, 2021). "We were further able to demonstrate that the mTOR, interleucin, and melatonin pathways are modified by herbal compounds which thus counteract cachexia." (PMID 32733236, 2020). "Salidroside, one of the primary functional ingredients of Rhodiola, has been reported to preserve muscle mass in the mouse cancer-cachexia model via activating mammalian rapamycin signaling (mTOR) and prevent the stress-induced repression of mTOR signaling." (PMID 31623349, 2019). "Taken together, our data demonstrate that cachexia in the ApcMin/+ mouse model is associated with a mild form of cardiac atrophy that may be caused by decreases in the rate of myofibrillar protein synthesis and the suppression of anabolic signaling through mTOR." (PMID 23589074, 2013).
Cachexia (continued). "To evaluate changes in cellular signaling involved in the regulation of protein synthesis, we measured IGF-1/Akt/mTOR pathway activation during the initiation and progression of cachexia." (PMID 21949739, 2011). "Phosphorylation of Foxo was reduced during initial and intermediate stages of cachexia, and the phosphorylation of mTOR was repressed after the initiation of cachexia." (PMID 21949739, 2011). "Despite the reduction in IGF-1 expression and mTOR signaling, we detected an increase in Akt phosphorylation as cachexia progressed." (PMID 21949739, 2011). "In the catabolic state of cachexia, mTOR activity is reduced and autophagy is increased." (PMID 40869331, 2025). "In summary, exercise counteracts muscle wasting in cachexia by simultaneously promoting muscle protein synthesis via the IGF-1/PI3K/Akt/mTOR pathway and suppressing excessive protein degradation mediated by the ubiquitin-proteasome and autophagy-lysosomal pathways." (PMID 40869331, 2025). "Moreover, TNF/IFN‐induced cachexia in C2C12 myotubes was reported to be reduced by unacylated ghrelin in a PI3K/ mammalian target of rapamycin (mTOR)‐dependent manner." (PMID 37661635, 2023). "The increased REDD1 expression was also associated with lower mTOR expression, suggesting that REDD1 may curb mTOR signaling during later stages of cachexia development." (PMID 34829914, 2021). "Hence, the mTOR, interleukin and melatonin pathways form essential components of both cachexia and the adaptogenic effect." (PMID 32733236, 2020). "For instance, the mechanistic target of rapamycin (mTOR), a major intracellular signaling intermediary, participates in cell growth by up-regulating anabolic processes such as protein and lipid synthesis thus counteracting cachexia." (PMID 32733236, 2020). "A trend for an additive anti-cachectic effect observed in the combination of CDD866 and everolimus would warrant further exploration as to how ActRII blockade and mTOR inhibition may positively interact on skeletal muscle undergoing cachexia." (PMID 27462398, 2016). "As expected from our assessment of mTOR phosphorylation and our findings of diminished protein synthesis rates, we observed that the amount of phosphorylated (active) S6rp and 4EBP1 were both diminished with cachexia." (PMID 23589074, 2013). "However, at 20 weeks of age phosphorylated mTOR expression was reduced by ∼21% (P<0.05), demonstrating a suppression of cardiac mTOR signaling during the progression of cachexia." (PMID 23589074, 2013). "The phosphorylation of mTOR target substrates, p70S6K and 4EBP1, corresponded with the reduction in myofibrillar protein synthesis throughout the progression of cachexia and are consistent with observations in other models of cancer cachexia." (PMID 21949739, 2011). "During the initiation of cachexia, there was a trend for mTOR phosphorylation on Ser residue 2448 to decrease (P = 0.06), while phosphorylation of mTOR targets, p70 (Thr389) and 4EBP1 (Ser65), were reduced 20% (P = 0.001) and 55% (P<0.001) during initial stages of cachexia, respectively." (PMID 21949739, 2011). "However, the data suggest that eIF2α phosphorylation-related attenuation of translation and mTOR/S6K1-dependent increase in protein synthesis may occur simultaneously in the liver at the onset of cachexia." (PMID 40124481, 2025). "Therefore, the present work analysed components of the mTOR cell signalling pathway under the influence of leucine, in the setting of cachexia; this is the first time that the effects of tumour development on muscle protein synthesis were analysed during the course of an experiment." (PMID 30975087, 2019). "Furthermore, treatment of endotoxin and interferon-γ to C2C12 myotubes has been shown to mimic several signaling events we observed in muscle during severe cachexia including the reduction in phosphorylated mTOR and p70S6k and the increase in phosphorylated raptor and activation of AMPK." (PMID 24285707, 2013).
Cachexia (continued). "Muscle IGF-1 mRNA expression and mTOR targets were suppressed with the progression of body weight loss, while muscle AMPK phosphorylation (Thr 172), AMPK activity, and raptor phosphorylation (Ser 792) were not increased with the initiation of weight loss, but were induced as cachexia progressed." (PMID 21949739, 2011). "During the later stage of cachexia, muscle AMPK is activated, which leads to mTOR signaling repression." (PMID 37217930, 2023). "Recently, it has been demonstrated that aerobic exercise successfully attenuated muscle atrophy, activated adiponectin signaling, increased mTOR phosphorylation, and suppressed light chain 3 (LC3-II) in a C26-induced cachexia model and C2C12 myotube model of cancer cachexia." (PMID 38791998, 2024). "Based on our previous literature review, cachexia is a complex syndrome connected with several signaling pathways, including TGF-β signaling activation, PI3K/Akt/mTOR signaling, the renin–angiotensin–aldosterone system (RAAS) pathway, myostatin and activin signaling, and the hypoxia/HIF-1 pathway." (PMID 38203330, 2023). "Moreover, the phosphatidylinositol-3 kinase (PI3K)/Akt/mammalian target of rapamycin (mTOR) pathway and forkhead box O (FOXO), which are general regulators of skeletal muscle mass homeostasis, are affected in cancer cachexia." (PMID 30275370, 2018). "Cachexia suppressed liver Akt and S6 phosphorylation, independent of mTOR, which was induced with cachexia progression." (PMID 25789991, 2015). "Its dual role in stimulating AKT/mTOR signaling and modulating myostatin-SMAD pathways highlights its potential as a candidate for combination therapy, potentially engaging novel feedback loops and receptor crosstalk mechanisms relevant to muscle regeneration and anti-cachexia strategies." (PMID 41302540, 2025). "Moreover, this may be a fully controlled response providing, for instance, in the counteraction of tumor-induced cachexia, the inhibition of catabolic pathways (IL-6, TNF-alpha) balanced with the stimulation of anabolic pathways (FoxO3a, p-AKT, p-mTOR, and P-GSK-3β)." (PMID 38004420, 2023). "Regardless of cachexia, PDTC treatment promoted an anabolic shift in muscle protein turnover through an induction in muscle mTOR signaling and protein synthesis, and reductions in Atrogin-1 protein expression." (PMID 27449092, 2016).
diabetic cardiomyopathy (36 papers, 2014 to 2025). Diabetic cardiomyopathy is a disorder of the heart muscle in people with diabetes. "Impairments of endothelin-1 (ET-1) signaling and mTOR pathway have been implicated in diabetic cardiomyopathies." (PMID 36430296, 2022). "Another factor that contributes to cardiomyocytes apoptosis is the mammalian target of rapamycin (mTOR) pathway which regulates cell growth, survival, and metabolism, and is also implicated in diabetic cardiomyopathy, where its dysregulation contributes to pathological cardiac remodeling." (PMID 40867548, 2025). "Crucially, the increased expression of miR-494 was associated with a decreased phosphorylation of the PI3K/AKT/mTOR pathway, which the authors proposed could potentiate the pathogenesis of diabetic cardiomyopathy." (PMID 39125612, 2024). "Defects in mTOR signalling are believed to contribute to metabolic dysfunctions in diabetic liver and hearts, but evidence is missing that mTOR activation is causal to the development of diabetic cardiomyopathy." (PMID 24408966, 2014). "The hyperactivation of mTOR in diabetic cardiomyopathy was suggested to happen through a hyperglycemic state, which worsens the disease progression and contributes to the exacerbation of the inflammatory condition." (PMID 40867548, 2025). "While sitagliptin has been shown to influence mTOR in various tissues, such as the liver and aorta, this study is the first to show its effect on mTOR expression in cardiac tissue especially concerning diabetic cardiomyopathy." (PMID 40867548, 2025). "This is the first study to document the inhibitory effect of sitagliptin on mTOR in a diabetic cardiomyopathy model." (PMID 40867548, 2025). "The anti-pyroptosis potential of metformin, albeit less studied, is obvious in terms of promising outcomes in diabetic cardiomyopathy through AMPK/mTOR pathway." (PMID 41244507, 2025). "One study showed that neuregulin-4 attenuates diabetic cardiomyopathy by regulating autophagy via the AMPK/mTOR." (PMID 38195474, 2024). "A recent study has found that aldehyde dehydrogenase 2 (ALDH2) can activate the PI3K/AKT/mTOR pathway to alleviate ischemia and reperfusion injury in diabetic cardiomyopathy." (PMID 38283744, 2023). "Neuregulin-4 attenuates diabetic cardiomyopathy by regulating autophagy via the AMPK/mTOR signalling pathway in type 1 diabetic mice." (PMID 36221104, 2022). "For the PI3K/Akt signaling pathway, the gene Sirt1 participates in diabetic myocardial injury and the occurrence and development of early diabetic cardiomyopathy by negatively regulating the PI3K/Akt/MTOR signaling pathway." (PMID 36141135, 2022). "The interplay between ET-1 signaling and mTOR under hyperglycemic conditions in cardiomyocytes needs to be further investigated to unveil potential drug targets to treat diabetic cardiomyopathies." (PMID 36430296, 2022). "Accumulating evidence has revealed that the AMPK/mTOR pathway plays a key role in the autophagy regulation of diabetic cardiomyopathy." (PMID 36221104, 2022). "Taken together, our data indicate that HMGA1 aggravates diabetic cardiomyopathy by directly regulating miR-222 promoter activity, which inhibits P27/mTOR-induced autophagy." (PMID 32123163, 2020). "However, our study is the first to reveal that sitagliptin induces cardioprotective effects, at least in part, through modulation of the mTOR–VEGF–FLT-1 axis in diabetic cardiomyopathy." (PMID 40867548, 2025). "Functional enrichment analysis showed that these hub genes were significantly enriched in cardiac function (e.g. diabetic cardiomyopathy and insulin signaling pathway), signaling (mTOR signaling pathway), oxygen metabolism (thermogenesis and oxidative phosphorylation), autophagy, and diseases." (PMID 40341377, 2025). "Moreover, mTOR inhibitors like rapamycin have protective effects against diabetic cardiomyopathy." (PMID 40867548, 2025).
diabetic cardiomyopathy (continued). "Numerous studies indicated that signaling pathways such as mTOR/AMPK, FOXOs, Nrf2, SIRTs, Parkin, and Atg gene products contribute to the regulation of diabetic cardiomyopathy by cellular autophagy." (PMID 40491718, 2025). "This protective effect against diabetic cardiomyopathy (DCM) is achieved through suppression of autophagy via activation of the lncRNA H19, ROS, and the PI3K/Akt/mTOR signaling pathway." (PMID 40491718, 2025). "Several pharmacotherapeutic agents have already been reported to protect against diabetic cardiomyopathy by triggering autophagy through AMPK activation and/or mTOR suppression." (PMID 36221104, 2022). "However, seven signaling pathways - Wnt, HIF1, TGF beta, IL17, mTOR, glucagon, and VEGF - along with pathways involved in diabetic cardiomyopathy and necroptosis, were exclusively enriched in the SITA group." (PMID 41282288, 2025). "Diabetic cardiomyopathy (DCM) exemplifies the interplay between metabolic derangements and PM dysregulation.In hyperglycemic conditions, disrupted ubiquitination destabilizes mTOR complexes, leading to heightened oxidative stress and apoptosis." (PMID 40734978, 2025). "Resveratrol, carnosic acid, beta carotene, and curcumin can activate autophagy through the SIRT1/FOXO1/Rab7 axis, PI3K/Akt/mTOR, activate AMPK and JNK1, phosphorylated Bcl-2 and Bim and subsequently disrupted their interactions with Beclin1 to treat diabetic cardiomyopathy." (PMID 37810881, 2023). "In conclusion, our study indicated that empagliflozin could protect diabetic cardiomyopathy by up-regulating PP2Cm, promoting catabolism of BCAA, and downregulating mTOR/p-ULK1, thereby up-regulating ULK1 and increasing autophagy." (PMID 37149696, 2023). "Empagliflozin may attenuate diabetic cardiomyopathy-related myocardial injury by promoting the catabolism of BCAA and inhibiting mTOR/p-ULK1 to enhance autophagy." (PMID 37149696, 2023). "Taken together, our results demonstrated that continued administration of 9-PAHSA alleviated diabetic cardiomyopathy in db/db mice.9-PAHSA treatment increased cardiac autophagy possibly via up-regulation of PI3KIII and BECN1 and down-regulation of mTOR and p-Akt in diabetic myocardium." (PMID 34867366, 2021).